BRAF (B-Raf proto-oncogene, serine/threonine kinase)
Diseases named in the same sentence as BRAF in open-access papers (continued):
Sharing a sentence is not in itself a finding about the gene and the disease.
melanoma (continued). "Similarly, a representative BRAF/NRAS wild-type melanoma was also not responsive to BRAF or MEK inhibitors." (PMID 31727958, 2019). "However, since only approximately 40–50% of melanoma cells harbor an activating BRAF mutation, there still remains a role for IFN-α in this setting as the remaining 50–60% of melanomas would not be susceptible to BRAF-targeted therapies." (PMID 30725205, 2019). "Considering that the majority of BRAF MUT patients had received BRAF and/or MEK inhibitors in prior lines, we were interested to see whether the performance of the test would be different in this subgroup of melanoma patients." (PMID 30925943, 2019). "However, the activity of MEK inhibitors in BRAF-mutant melanoma has not been replicated in other genotypes." (PMID 30428063, 2019). "The use of BRAF as a predictive biomarker for mCRC is limited at this time and the use of single agent BRAF inhibitors does not demonstrate the same effects as seen in melanoma." (PMID 30646508, 2019). "However, melanoma patients with wild-type BRAF (BRAF-wt) have fewer treatment choices, as they do not benefit from BRAF inhibitor therapy." (PMID 30428063, 2019). "To improve its therapeutic efficacy and overcome drug resistance in advanced melanomas, we synthesized Tris DBA-Pd hyaluronic acid nanoparticles (Tris DBA-Pd HANP) and evaluated them against in vivo xenografts of LM36R, an aggressive BRAF mutant human melanoma resistant to BRAF inhibitors." (PMID 30824801, 2019). "Patients with melanoma brain metastases may benefit from systemic therapy using BRAF-inhibitors with and without trametinib." (PMID 31803366, 2019). "In contrast to BRAF-mutated melanoma, no approved targeted therapies exist for NRAS-mutated melanoma, but positive phase III data on PFS have been reported for a study comparing the efficacy of binimetinib (MEK162) versus dacarbazine in unresectable or metastatic NRAS-mutated melanoma (NEMO study)." (PMID 30956763, 2019). "Thus, exploiting specific inhibition of ERK1/2 signalling and apoptotic priming in BRAF-mutant cells coupled with the pro-survival bias towards MCL1 could afford a large therapeutic window and further improve patient outcomes in melanoma." (PMID 31727888, 2019). "More importantly, TNFα failed to activate BRAF in PPP2R2A-depleted melanoma cells." (PMID 31015455, 2019). "Therefore, BRAF and MEK inhibitor combinatorial treatments, in the form of trametinib + dabrafenib and cobimetinib + vemurafenib, were approved by the FDA for patients with advanced BRAFV600E melanoma." (PMID 31426419, 2019). "However, while vemurafenib is FDA-approved for BRAF-V600E melanomas, the non-melanoma basket trial was unsuccessful, suggesting mutation status is insufficient to predict response." (PMID 31672130, 2019). "To test the hypothesis that BRAF/MEK inhibitors could sensitize melanoma cells to MCL-1 inhibitors, we compared the effects of A1210477 given before versus after BRAF inhibitor treatment in A375M melanoma cells." (PMID 31727958, 2019). "Many of these mutants show a lower BRAF kinase activity toward MEK in vitro than that of the V600E mutant, explaining why these mutants are often classified as “low activity” or “impaired activity” mutants (for example, G469A and D594G are found frequently in mucosal melanomas)." (PMID 31398831, 2019). "The patient was diagnosed with two primary, BRAF-negative, stage IV melanomas." (PMID 30858407, 2019). "For example, in other neoplastic diseases driven by activated BRAF, such as melanoma, expression of this strong oncogene in normal precursor cells leads to oncogene-induced senescence, presumed to be an organism-level protective response to oncogenic transformation." (PMID 31527903, 2019). "Although BRAF and NRAS are frequently mutated in human melanoma, coexistence of BRAF c.1799T>A(V600E) and NRAS c.181C>A (Q61K)/182A>G (Q61R) changes within the same melanoma tumor is essentially nonexistent except in situations of acquired resistance to BRAF inhibitors." (PMID 30651601, 2019).
melanoma (continued). "BRAF inhibitors failed to eradicate melanoma due to immune evasion to some extent." (PMID 31134073, 2019). "Here, we confirm these observations and additionally, our study highlights the efficacy of this combination especially on melanoma cells rather than healthy surrounding cells, and also importantly in the context of acquired and intrinsic BRAF inhibitor resistance." (PMID 30728057, 2019). "Interestingly, activation of the Akt pathway rescued the effect of magnolol in BRAF‐ and NRAS‐mutant melanoma cells suggesting magnolol might primarily be acting through the PI3K/Akt pathway." (PMID 30793515, 2019). "In NFATc2+ EZH2+ melanoma cell lines pharmacological co-targeting of NFATc2 and EZH2 exerted strong anti-proliferative and pro-apoptotic activity, irrespective of BRAF or NRAS mutations and of BRAF inhibitor resistance." (PMID 30710146, 2019). "Taking melanoma as an example, some patients with melanoma have been clinically found to have poor outcomes when given BRAF/MEF inhibitors, and further studies have found that the tyrosine kinase receptor AXL is highly expressed on the surface of tumor cells that react poorly to BRAF/MEF inhibitors." (PMID 30849971, 2019). "Here, we exploit matched patient-derived melanoma cell lines from treatment-naive, treatment-sensitive, and NRASQ61K-based resistant tumor states established from patient-derived tumor xenografts to study BRAF-resistance-driven alterations in kinase activation states." (PMID 31521607, 2019). "This analysis of BRAFi/MEKi combinations for BRAF-mutant melanoma, while limited as not a direct head-to-head clinical trial, highlights the differences in tolerability and efficacy that may be useful for therapeutic decision making." (PMID 31653096, 2019). "According to the definition in the “materials and methods” section, 60% of the malignant melanoma group expressed BRAF V600E, and thus a significant difference in intensity of BRAF V600E staining between melanoma and non-melanoma skin cancers was found (P<0.001)." (PMID 31531096, 2019). "This was independent of the BRAF/NRAS mutation status, and suggests that PAX3 induced MITF expression is an inherent melanocyte lineage trait that is conserved in melanoma independently of the genetic background." (PMID 30277012, 2019). "Finally, the combination of BRAF and ALK inhibitor treatments of mice bearing ALK-positive melanoma tumours dramatically reduced tumour volumes, making ALK an exciting clinical target in melanoma patients." (PMID 30290811, 2018). "Thus, multiples pathways under the control of BRAF might converge to oppose PGC-1α and OXPHOS in subsets of melanoma." (PMID 29629336, 2018). "To date, there are no data with ipilimumab, nivolumab, pembrolizumab, or BRAF-targeted therapy (either single-agent BRAF inhibitors or combined BRAF/MEK inhibitor therapy) to justify the use of these agents/regimens in patients with stage II melanoma." (PMID 29848375, 2018). "Additionally, BRAF therapy is contraindicated for patients with BRAF wildtype melanoma und thus this treatment is not feasible for roughly half of the patients." (PMID 29432466, 2018). "It was also shown that in low but not in high activity BRAF mutant melanoma cell lines (WM3670, WM3629) sorafenib treatment could reduce tumor growth and induce apoptosis." (PMID 29739364, 2018). "However, we previously showed that VEM is not very effective against a BRAF-V600E melanoma mutant in a patient-derived orthotopic xenograft (PDOX) model." (PMID 29416666, 2018). "Deliberately disrupting or inhibiting ABCB5 in melanomas might not be sufficient to improve the therapeutic resistance to BRAF inhibitors." (PMID 29929490, 2018). "SR4 and niclosamide inhibited melanoma proliferation irrespective of BRAF/NRAS status." (PMID 30651927, 2018).
melanoma (continued). "Patient 1 is a 75-year old male, who was originally diagnosed with stage IIIB, BRAF-negative melanoma of the upper back and left axillary lymph node (LN) involvement in 2012, treated with wide local excision (Breslow thickness: 2.9 mm) and axillary LN dissection." (PMID 30305172, 2018). "Additionally, we included BRAF, GNAQ and KIT mutant melanoma cells in our analyses." (PMID 30405888, 2018). "RIP1-mediated resistance of melanoma cells to BRAF/MEK inhibitors was due to its inhibitory effect on induction of apoptosis, as RIP1 silencing promoted activation of the caspase cascade and a general caspase inhibitor abolished enhancement of killing of melanoma by silencing of RIP1." (PMID 29880840, 2018). "In contrast, BRAF mutant colorectal cancers that count for approximately 10% of all cases, show only a marginal response rate of 5%, suggesting that colorectal cancers have an intrinsic resistance mechanism that appears to be absent or less common in melanoma." (PMID 29192388, 2018). "We chose to investigate this hypothesis using a spontaneous metastasis xenograft model of human BRAF-wildtype melanoma in scid mice (lacking functional T and B cells), modeling the whole metastatic cascade." (PMID 30089785, 2018). "No somatic alterations in BRAF were identified within any platform in our canine melanoma cohort." (PMID 30188888, 2018). "Additionally, the results from our xenograft model with a BRAF wildtype human melanoma cell line show that the effect is obviously independent of mutated BRAF." (PMID 30089785, 2018). "Nonetheless, 17-AAG inhibited melanoma cell proliferation regardless of BRAF mutational status, perhaps due to these cells’ dependence upon CRAF signaling in melanomas with activating NRAS mutations as well as activation of CRAF by BRAFWT under these conditions." (PMID 29481571, 2018). "In the absence of ALKRES, resistant melanoma cells respond again to both BRAF and MEK inhibitors." (PMID 30290811, 2018). "In addition, RIP1 kinase activity was not required for melanoma cells to survive BRAF/MEK inhibition as RIP1 mediated NF-κB activation through its intermediate domain." (PMID 29880840, 2018). "In addition, the ERK1/2/SOX10/FOXD3 axis appears to be specific to mutant BRAF melanoma cells since N-RAS mutant melanoma cells have no detectable level of basal or induced FOXD3 expression." (PMID 29295999, 2018). "In any case, the function of TCF19 in NRAS‐mutant melanoma, especially in BRAF/MAPK inhibitor and immune therapy resistance, is worthy to study further to better understand the mechanisms of how TCF19 is upregulated in NRAS‐mutant melanoma and how it governs the resistance to immune therapy." (PMID 29661909, 2018). "However, not all BRAF-mutant melanomas respond to targeted therapy and responses that do occur are often brief and followed by the emergence of drug-resistant disease." (PMID 30188888, 2018). "The capacity of NF1 mutations to act both cooperatively and exclusively without BRAF and NRAS mutations in melanoma may be mediated through pathways other than the MAPK pathway." (PMID 28637487, 2017). "Indeed, we showed that BRAF but not CRAF plays a critical role during the initiating stages of melanoma formation." (PMID 28497782, 2017). "The role of ARAF in NRAS-induced melanoma has not been a matter of intense investigation mainly because of the well-described paradoxical effects of RAF inhibitors in RAS-mutated tumours, which is thought to rely mostly on BRAF and CRAF dimerization." (PMID 28497782, 2017). "In summary, CDK4 inhibitor palbociclib may be a strong inhibitor of melanoma cell proliferation in the absence of BRAF and NRAS mutations in melanomas with homogeneous CDK4 expression." (PMID 27903987, 2017). "We surveyed kinome expression patterns across sub-populations of the BRAF/NRAS wild type sample and found that CDK4 and CDK2 were consistently highly expressed in the majority of cells, suggesting that these kinases might be involved in melanoma progression." (PMID 27903987, 2017).
melanoma (continued). "Unfortunately, Sorafenib failed to be a specific inhibitor for mutant BRAF melanomas." (PMID 28537899, 2017). "In conclusion, our study identified EZH2 gain as a biomarker for selecting patients with BRAF V600E-mutated melanoma who may benefit from combination therapy with BRAF and EZH2 inhibitors, thus providing insights into a promising novel therapeutic strategy for the treatment of melanoma." (PMID 29202777, 2017). "Our results show that in melanoma cells the expression of both PMCA4b and PMCA1 is under epigenetic control and the elevation of PMCA4b expression either by HDACi treatment or by the decreased activation of the BRAF-MEK-ERK pathway can inhibit the migratory capacity of the highly motile A375 cells." (PMID 28596940, 2017). "Furthermore, DCA has been shown to inhibit the growth of a range of melanoma cell lines, independent of BRAF status and PLX4032 sensitivity." (PMID 29137417, 2017). "We addressed in this study (i) the RSK activity in BRAFV600E/K inhibitor resistant melanoma cells, (ii) the effect of RSK inhibition on the viability of BRAFV600E/K and MAPK inhibitor resistant cells and (iii) the impact of the RSK target YB-1 on the sensitivity towards BRAF inhibition." (PMID 28415756, 2017). "But, whilst mutant NF1 is known to cooperate with RASopathy genes (RASA2, PTPN11, SOS1, RAF1 and SPRED1) in melanoma and although NF1 is found to be frequently mutated (25–30%) in melanomas harbouring wild-type BRAF and NRAS, it is curious that melanoma is not a tumour type associated with NF1." (PMID 28637487, 2017). "In the same way that melanoma has been postulated to share resistance mechanisms to both BRAF and MEK inhibitors, a major limitation to the success of future combination therapies, could be conferred resistance to BRAF/MEK inhibitors and immunotherapy." (PMID 29100459, 2017). "We conducted a meta regression analysis to examine whether incidence of cuSCC varied by specific BRAF inhibitor, melanoma versus non-melanoma, or study design." (PMID 29137342, 2017). "However, the median survival in stage IV disease was shorter in patients with BRAF-mutant melanoma and not treated with a BRAF inhibitor than in the wild type (WT) situation." (PMID 28797232, 2017). "In this report, we present evidence that upregulation of CD47 expression is an important immunosuppressive mechanism triggered by BRAF/MEK inhibitors that prevents macrophage phagocytosis of melanoma cells, and may thus contribute to impairment of anti-melanoma T cell responses." (PMID 29050218, 2017). "However, feedback activation of EGFR upon BRAF blockade in BRAFmut CRC cells results in a minimal response to selective BRAF inhibitors with only 5% of patients responding, compared to an 80% response rate in BRAFV600E melanoma patients." (PMID 27999210, 2017). "A study looking into metabolic changes in BRAF‐induced senescent cells did however find that depletion of pyruvate dehydrogenase kinase 1 (PDK1), a gatekeeper gene linking glycolysis to oxidative phosphorylation, selectively killed BRAFV600E‐mutant melanoma cells both in vivo and in vitro." (PMID 28097822, 2017). "Also, we assessed the clinical implication of BRAF, RAS, NF1, and triple‐wild‐type melanomas." (PMID 28267273, 2017). "To investigate whether targeting BRAF with PLX4032 would restore the sensitivity to ATRA, we treated the BRAFV600E-mutant melanoma cell lines with PLX4032 at a concentration close to the IC50 values in combination with increasing concentrations of ATRA (0.1-25 μM)." (PMID 29137417, 2017). "Furthermore, the c-Met receptor to which HGF binds exclusively is expressed and activated in melanoma cells and tumours, especially in those that harbour the NRAS mutation and non-mutated BRAF." (PMID 28708099, 2017).
melanoma (continued). "So these results suggest that NRF-1-mediated regulation of CD47 expression is a novel mechanism by which ERK signalling promotes the pathogenesis of melanoma, and that the combination of CD47 blockade and BRAF/MEK inhibitors may be a useful approach for improving their therapeutic efficacy." (PMID 29050218, 2017). "As such, the HGF/SF GEMM may better model the other 50% of human melanomas not expressing mutant BRAF." (PMID 28788083, 2017). "NF1 suppression can lead to increased RAS activation in melanoma, which may explain the lack of correlation between ERK phosphorylation and BRAF mutational status." (PMID 28938534, 2017). "In addition to BRAF WT melanomas, IDH2 levels were also assessed in BRAF V600E mutant melanomas." (PMID 29290954, 2017). "Therefore, combination therapy with BRAF and EZH2 inhibitors may be particularly beneficial to patients with mucosal and unknown primary melanoma." (PMID 29202777, 2017). "The results here suggest that the use of this combination is a promising treatment strategy for melanoma regardless of the mutation status of BRAF or NRAS, and it may overcome melanoma's resistance to current treatments." (PMID 27829238, 2016). "Thus, in spite of the ground breaking progresses in melanoma treatment, relapse and lack of treatment options for BRAF-WT patients remains a crucial issue." (PMID 27829238, 2016). "Furthermore, our results strongly suggest that RUNX2 might be a mediator of resistance to BRAF V600E targeted therapy, involving RTK up-regulation and activation in melanoma." (PMID 27102439, 2016). "It will be interesting to determine whether this loop and the signaling bypass created by BRAF-dependent PAX3 phosphorylation is also operative in other tissues and in cancer cells such as rhabdomyosarcoma and melanoma cells, which would offer new refined therapeutic approaches." (PMID 27906130, 2016). "Consequently, our work demonstrates that CD70 ectopic expression in melanomas is not a valuable biomarker to predict tumor cells sensitivity to BRAF V600 inhibitors." (PMID 26828592, 2016). "Currently, in addition to BRAF inhibitors (e.g., Vemurafenib and Dabrafenib), several other targeted inhibitors, including MEK inhibitors (e.g., Trametinib and Cobimetinib) and PI3K inhibitors (e.g., BEZ235), are being evaluated in clinical trials for treatment of melanoma patients." (PMID 26928089, 2016). "For example, NF-κB pathway activation could confer resistance to MAPKi in BRAF-mutant melanoma, but did not score as a resistance pathway in many other cancer types." (PMID 27738492, 2016). "In addition, we find that the observed response is present for BRAF-mutated, but not NRAS-mutated melanoma cells, supporting these responses as on-target effects of the BRAF inhibitors." (PMID 27648299, 2016). "Not surprisingly, BRAF inhibitors deeply alter the metabolism of melanoma cells." (PMID 27250023, 2016). "Notably, knockdown of IFI6 in BRAF-mutant, NF1-deficient, or triple wild-type melanoma did not alter the expression of E2F2 or its target genes." (PMID 27608486, 2016). "In melanocytes, deficient autophagy may contribute to the development or progression of melanoma, but is likely not sufficient to cause melanoma in the absence of a RAS or BRAF activating mutation." (PMID 27655644, 2016). "To test the hypothesis that expression of MCL-1, a known anti-apoptotic factor, can contribute to drug resistance, we targeted MCL-1 using a small molecule inhibitor (sabutoclax) in a variety of human melanomas, including BRAFV600E and non-BRAF stage III/stage IV metastatic melanoma cell lines." (PMID 27846237, 2016).